CYTOR (cytoskeleton regulator RNA)
Synonyms: MGC4677; C2orf59; LINC00152; NCRNA00152
Gene: Long non-coding RNA gene on chromosome 2 (87,454,781 to 87,636,740, forward strand). Ensembl gene ENSG00000222041.
Diseases named in the same sentence as CYTOR in open-access papers:
CYTOR is named in the same sentence as 76 diseases in open-access papers, as found by Europe PMC text mining. Sharing a sentence is not in itself a finding about the gene and the disease. The quoted sentences say what the papers report.
gastric cancer (44 papers, 2015 to 2025). A primary or metastatic malignant neoplasm involving the stomach. "In gastric cancer, CYTOR is up-regulated and can promote tumor growth through the epidermal growth factor receptor (EGFR)-mediated PI3K/PKB pathway." (PMID 40308216, 2025). "Cytoskeletal regulator RNA, known as CYTOR, is aberrantly overexpressed in various highly malignant cancers, including breast cancer, colorectal cancer, gastric cancer and non-small cell lung cancer cells." (PMID 33621953, 2021). "For example, LINC00152/CYTOR (identified within this class) binds and recruits EZH2 to its target promoters p15 and p21 in gastric cancer and IL24 in lung cancer and thereby causes repression of their expression." (PMID 29757368, 2018). "In addition, CYTOR was found to be a poor prognostic factor for gastric cancer, non-small-cell lung cancer, breast cancers, and nasopharyngeal carcinoma." (PMID 36452343, 2022). "CYTOR is also up-regulated in colon cancer and gastric cancer." (PMID 36060256, 2022). "Recently, the aberrant expression of CYTOR has been reported in some types of cancers including gastric cancer, hepatocellular carcinoma, colon cancer, gallbladder cancer and renal cell carcinoma, in which it may act as an oncogene." (PMID 30064438, 2018). "Previous studies have shown that expression of CYTOR was increased in gastric cancer, renal cell carcinoma (RCC) and gallbladder cancer, as compared to paired non-neoplastic tissues, high CYTOR expression was positively associated with lymph node metastasis, high TNM stage, and poor over survival." (PMID 29108264, 2017). "Up-regulated CYTOR could also be detected in plasma and exosomes from gastric cancer patients, it might act as novel blood-based biomarker for diagnosis of gastric cancer." (PMID 29108264, 2017). "CYTOR could promote gastric cancer cell cycle progression through binding to EZH2 and regulating p15 and p21." (PMID 29108264, 2017). "In gastric cancer patients, plasma levels of urothelial cancer associated 1 (UCA1/CUDR), long stress-induced non-coding transcript 5 (LSINCT-5), phosphatase and tensin homolog pseudogene 1 (PTENP1), and cytoskeleton regulator RNA (CYTOR/LINC00152) were higher than in healthy individuals." (PMID 29614786, 2018). "CYTOR, also known as LINC00152, is a lncRNA with a length of 828 nucleotides and expressed abnormally in many cancers, such as lung cancer, stomach cancer, colon cancer, etc.." (PMID 34039336, 2021). "CYTOR (LINC00152) is a long non-coding RNA that regulates cytoskeleton and plays an oncogenic role in several cancers, including colorectal cancer, and gastric cancer." (PMID 31806013, 2019). "Our results indicated that CYTOR probably acts as a proto-oncogene in CRC, which is similar to its role in lung cancer, gastric cancer, and other cancers." (PMID 30064438, 2018). "Proteins interacting with CYTOR had been investigated in other cancer types; for example, EZH2 and EGFR were reported to interact with CYTOR in gastric cancer." (PMID 30064438, 2018). "Levels of LINC00152, also known as cytoskeleton regulator RNA (CYTOR), have been shown to be increased in gastric cancer tissue." (PMID 28719640, 2017).
colon cancer (30 papers, 2017 to 2025). "The lncRNA CYTOR is significantly upregulated in colon cancer tissue samples and is associated with poor prognosis." (PMID 36719027, 2023). "Consistently, CYTOR expression is associated with the loss of epithelial features and the acquisition of mesenchymal characteristics in multiple colon cancer cell lines." (PMID 33246471, 2020). "For example, CYTOR and the corresponding protein binding can contribute to the metastasis of colon cancer, and HOXB-AS3 expression can inhibit the growth of colon cancer." (PMID 38233788, 2024). "The complex formed by the CYTOR-nucleolin interaction activates signaling pathways that promote colon cancer progression." (PMID 36719027, 2023). "CYTOR was reported to be significantly upregulated and resistant to oxaliplatin induced apoptosis in colon cancer." (PMID 35081873, 2022). "One study demonstrated that inhibition of CYTOR retards the migration and invasion of colon cancer cells, while overexpression of CYTOR promotes colon cancer cell metastasis." (PMID 33246471, 2020). "Mechanistically, CYTOR enhances cell invasion and metastatic properties by interacting with β-catenin in colon cancer." (PMID 33246471, 2020). "For example, the expression of CYTOR is significantly elevated in colon cancer." (PMID 35081873, 2022). "Cytoskeleton regulator RNA (CYTOR), also named Linc00152, is upregulated in colon cancer patients and may be a predictive factor of a worse prognosis." (PMID 33246471, 2020). "CYTOR overexpression leads to resistance to oxaliplatin-induced apoptosis in colon cancer cells." (PMID 33246471, 2020). "For example, CYTOR sponged miRNA-103a-3p to promote malignant progression of glioma stem cells, modulated the expression of miR-193a-3p to confer resistance to oxaliplatin in colon cancer, and negatively regulated miR-205 to promote renal cell carcinoma progression." (PMID 30064438, 2018). "The lncRNA CYTOR has been reported to regulate L-OHP resistance and promote EMT in colon cancer cells via miR-378a-5p/SERPINE1." (PMID 35359593, 2022). "The loss of epithelial characteristics and the simultaneous gain of mesenchymal features are correlated with CYTOR expression, the upregulation of which triggers EMT in colon cancer cells." (PMID 33246471, 2020). "CYTOR expression levels are correlated with TNM stage, disease-free survival and overall survival rates in patients with colon cancer." (PMID 33246471, 2020). "Therein, four lncRNAs including CYTOR, MEG3, MIR100‐HG and MIR31HG have been previously reported to play an oncogenic role in colon cancer." (PMID 31989761, 2020). "The wound-healing assay showed that CYTOR knockdown inhibited the migration of HCT8 and SW620 cells, and the depletion of CYTOR colon cancer cells failed to induce further invasion." (PMID 34778084, 2021). "The lncRNA cytoskeleton regulator RNA (CYTOR) facilitates epithelial-to-mesenchymal transition (EMT) and metastasis in colon cancer via interacting with β-catenin, which predicts poor prognosis and may be promising therapeutic target of colon cancer." (PMID 32117736, 2020).
colorectal cancer (28 papers, 2017 to 2024). A primary or metastatic malignant neoplasm that affects the colon or rectum. "Among the lncRNAs investigated, CYTOR was upregulated in colorectal cancer samples and associated with poor prognosis, having a role in proliferation and metastasis." (PMID 35359880, 2022). "CYTOR was highly expressed in colorectal cancer and is associated with prognosis." (PMID 33318318, 2020). "LINC00152 (ENSG00000222041, CYTOR) promotes colorectal cancer metastasis by interacting with β-catenin." (PMID 35959377, 2022). "It was reported that CYTOR positively regulated NRP1 expression by sponging with miRNA-206 in colorectal cancer, and miRNA-206 was significantly increased in human OA chondrocytes." (PMID 33749514, 2021). "In colorectal cancer cells, CYTOR promoted the proliferation of tumor cells and was considered to be an oncogene." (PMID 33318318, 2020). "CYTOR modulated proliferation, migration, invasion of colorectal cancer, head and neck squamous cell carcinoma." (PMID 31739287, 2019). "The aim of this study was to investigate the clinical significance, biological function and interacting partners of CYTOR in colorectal cancer (CRC)." (PMID 30064438, 2018). "By interacting with NCL and Sam68, the lncRNA CYTOR promotes colorectal cancer development." (PMID 35646114, 2022). "Funnel plots further showed no bias among these databases, which confirmed that CYTOR was a risk factor for survival in colorectal cancer." (PMID 30064438, 2018). "Thus, the combination of both CRNDE and CYTOR dysregulation could enforce the possible protection of RPE cells from DGI by the reduction of glucose intracellular intake and metabolism, as already discussed in relationship with colorectal cancer." (PMID 32326576, 2020).
breast carcinoma (27 papers, 2017 to 2025). "CYTOR promotes the proliferation and migration of breast cancer cells, and high expression of CYTOR is associated with relapse-free survival in patients with breast cancer." (PMID 32486413, 2020). "Additionally, CYTOR has been implicated in breast cancer resistance to tamoxifen, where it enhances tumor cell survival by aberrantly activating the MAPK/ERK signaling cascade, a key pathway in tumor proliferation and drug resistance." (PMID 41031251, 2025). "Among the numerous lncRNAs implicated in drug resistance, MALAT1, UCA1, CYTOR, and HOTAIR have emerged as crucial oncogenes, and GAS5 is a well‐known lncRNA that acts as a tumor suppressor in breast cancer." (PMID 41031251, 2025). "CYTOR, also known as LINC00152, was upregulated in breast cancer and related with advanced stage, lymphatic invasion, and shorter OS of patients." (PMID 37543427, 2023). "Curiously, the upregulated expression of CYTOR has been reported not only in vitro models but also in patients with several breast cancer classes such as HER2 or triple negative carcinomas subtypes." (PMID 35447891, 2022). "CYTOR was also shown to be required for breast cancer cell proliferation, migration, and cytoskeletal organization." (PMID 31750242, 2019). "lncRNA CYTOR (LINC00152) was revealed to be up-regulated in breast cancer and associated with poor survival of breast cancer patients." (PMID 31750242, 2019). "CYTOR could facilitate breast cancer growth and tamoxifen resistance by targeting KLF5 and miR-125a-5p." (PMID 37543427, 2023). "Silencing of CYTOR restored tamoxifen sensitivity of tamoxifen-resistant breast cancer cells." (PMID 36358625, 2022). "In addition, it has been noted that microRNA (miR)-125a-5p binds to CYTOR, and the expression of miR-125a-5p is negatively correlated with CYTOR in breast cancer tumor tissues." (PMID 36358625, 2022). "Increased expression of LINC00473 in HNSCC; LINC00114, MINCR and PVT1 in NPC; Linc-RA1 in glioma; LINC00473and CYTOR in NSCLC; NEAT1 and LINC00958 in cervical cancer; H19 in cardiac cancer; LINC02582 in breast cancer; and TUG1 in bladder cancer were associated with radioresistance." (PMID 36323697, 2022). "NEAT1 has been shown to be involved in many cancers, and promotes chemoresistance in TNBC, while early studies on the lncRNA CYTOR (also known as LINC00152) have shown it may regulate signalling in breast cancers." (PMID 34681087, 2021). "MALAT1, UCA1, CYTOR, HOTAIR, and GAS5 expressions were compared between breast cancer patients treated with tamoxifen alone (control) and those treated with tamoxifen plus NanoCurcumin (target group)." (PMID 41031251, 2025). "It has further been reported that, together with CYTOR, and MAPTAS1, MIR4458HG was an independent prognostic factor in breast cancer patients (10.21203/rs.2.24062/v1, preprint), with high expression associated with lower hazard ratios." (PMID 38253617, 2024). "CYTOR could activate Hippo and MAPK pathways via regulation of miR‐125a‐5p to enhance breast cancer cell survival upon tamoxifen treatment, indicating that targeting CYTOR may be a possible approach in reversing tamoxifen resistance in breast cancer." (PMID 32779318, 2020). "For instance, Liu et al50 found that CYTOR was among the most dramatically upregulated lncRNA in tamoxifen‐resistant breast cancer cells and in patient tissues with no response to tamoxifen treatment." (PMID 32779318, 2020). "Moreover, CYTOR is upregulated in tamoxifen-resistant breast cancer cell lines derived from MCF7, and CYTOR functions as a ceRNA by sponging miR-125a-5p, and upregulates a target of miR-125a-5p, the serum response factor (SRF), which promotes the tamoxifen resistance and cell proliferation." (PMID 32486413, 2020).
breast carcinoma (continued). "Moreover, emerging evidence has pointed out that CYTOR is not a breast cancer specific lncRNA, showing upregulated expression in several other types of cancer such as nasopharyngeal, gastric, colon, or hepatocellular carcinoma and also correlating with poor prognoses and increased aggressiveness." (PMID 35447891, 2022).
hepatocellular carcinoma (22 papers, 2017 to 2025). A malignant tumor that arises from hepatocytes. "Multiple studies recently reported pro‐oncogenic effects driven by CYTOR in breast, stomach, colon and hepatocellular cancers." (PMID 39960339, 2025). "LncRNA CYTOR affects the proliferation, cell cycle and apoptosis of hepatoma cells by regulating the miR-125b5p/KIAA1522 axis." (PMID 36891150, 2023). "This study investigated the function of long non-coding RNA (lncRNA) cytoskeleton regulator RNA (CYTOR) in hepatocellular carcinoma (HCC)." (PMID 35081873, 2022). "For example, CYTOR promotes the proliferation and cell cycle of hepatoma cells and inhibits the apoptosis of hepatoma cells through miR-125b-5p/KIAA1522 axis." (PMID 35911380, 2022). "We aimed to investigate whether lncRNA CYTOR could sponge miR-125b-5p to affect hepatocellular carcinoma (HCC) cells through targeting KIAA1522." (PMID 33318318, 2020).
glioma (18 papers, 2017 to 2023). A benign or malignant brain and spinal cord tumor that arises from glial cells (astrocytes, oligodendrocytes, ependymal cells). "As an example for clinical significance of this result, we identify CYTOR as a poor prognosis factor in gliomas with IDH mutation." (PMID 31806013, 2019). "To assess the methylation state of the CYTOR locus, we utilized data from 68 gliomas with IDH mutation profiled using the Illumina Infinium MethylationEPIC BeadChip (EPIC) arrays as a part of the DNA-methylation based classification efforts of central nervous system tumor entities." (PMID 31806013, 2019). "However, our integrative data indicates that a subset of IDHmut-codel tumors also harbors an open chromatin for CYTOR and having an open promoter might be indicative of a malignant subpopulation associated with progression within Grade II IDHmut-codel gliomas." (PMID 31806013, 2019). "Finally, we asked whether CYTOR expression was correlated with overall survival in gliomas with IDH mutation (WHO Grade II-III)." (PMID 31806013, 2019). "Furthermore, we identify CYTOR as a poor prognosis factor in gliomas with IDH mutation." (PMID 31806013, 2019). "CYTOR, NEAT1, LOXL1-AS1, and ZNF295-AS1 were significantly associated with glioma grade and survival." (PMID 36597408, 2023). "In comparison with expression levels of lncRNAs in low grade glioma, CYTOR and MIR155HG were significantly over-expressed in GBM tissues, while three lncRNAs (LINC00641, AC120036.4, PWAR6) were remarkably down-regulated in GBM samples." (PMID 33750353, 2021). "Recent research reveals overexpression of CYTOR in glioma tissues correlated with metastasis and knockdown of CYTOR can attenuate the tumor cell proliferation and invasion." (PMID 33750353, 2021). "CYTOR is associated with poor prognosis and is upregulated in diffuse gliomas, and higher grade IDH wild-type gliomas and glioblastomas." (PMID 31806013, 2019). "Both of these probes were significantly hypermethylated in IDHmut-codel samples when compared to IDHmut-noncodel samples, further suggesting the limited chromatin accessibility of CYTOR in IDHmut-codel gliomas." (PMID 31806013, 2019). "Finally, five lncRNAs (CYTOR, MIR155HG, LINC00641, AC120036.4 and PWAR6) were chosen to establish a risk score system for prediction the prognosis of gliomas." (PMID 33750353, 2021). "LncRNA CYTOR was up-regulated in glioma cells and tissues, and CYTOR overexpression partially reversed the inhibition of UPF1 on the proliferation and migration of glioma." (PMID 33318318, 2020). "Our studies first identified differentially expressed lncRNAs in glioma based on gene expression profiling, and focused on the lncRNAs PVT1, CYTOR, HAR1A and MIAT for further analysis." (PMID 29108264, 2017). "Further analysis of TCGA and GEO data revealed that the expressions of PVT1 and CYTOR were up-regulated, while HAR1A and MIAT expressions were down-regulated in gliomas." (PMID 29108264, 2017). "This study focused on identifying differentially expressed lncRNAs in gliomas based on gene expression profiling, and chose certain lncRNAs PVT1, CYTOR, HAR1A and MIAT, which changed with significant differences." (PMID 29108264, 2017). "In the TCGA, CGGA and Our datasets, differential expression analysis showed that CYTOR and MIR155HG were significantly overexpressed in GBM compared to LGG samples, while AC120036.4, LINC00641 and PWAR6 showed an inverse expression pattern in glioma samples." (PMID 33750353, 2021). "PVT1 and CYTOR expressions were remarkably increased in glioma samples compared with non-tumor controls (both P <0.001)." (PMID 29108264, 2017).
lung adenocarcinoma (14 papers, 2017 to 2025). A carcinoma that arises from the lung and is characterized by the presence of malignant glandular epithelial cells. "CYTOR is known to be up-regulated in many different cancers, including gastric, lung adenocarcinoma, renal cell carcinoma, and other cancers, and its expression is significantly associated with poor survival as well as lymph node metastasis." (PMID 40308216, 2025).
gallbladder cancer (11 papers, 2017 to 2024). "As a member of the lncRNA family, CYTOR was highly expressed in non-small cell lung cancer, gallbladder cancer and other malignant tumor tissues." (PMID 33318318, 2020).
non-small cell lung carcinoma (9 papers, 2019 to 2023). A group of at least three distinct histological types of lung cancer, including non-small cell squamous cell carcinoma, adenocarcinoma, and large cell carcinoma. "In non-small cell lung cancer, lncRNA CYTOR upregulated radioresistance via miR-206/PTMA axis, and PTMA (prothymosin alpha) involved in inhibiting apoptosis." (PMID 35600868, 2022). "CYTOR sponges miR-195 to promote the proliferation, migration and invasion of non-small cell lung cancer cells, and to induce cell resistance to radiation." (PMID 33318318, 2020). "In non-small cell lung cancer, CYTOR promoted proliferation and invasion of tumor cells and increased resistance to radiation therapy." (PMID 33318318, 2020). "Besides, lncRNA CYTOR sponges miR-195 to modulate proliferation, migration, invasion, and radio-sensitivity in non-small cell lung cancer cells." (PMID 36478088, 2023). "However, lncRNA CYTOR reduces radiosensitivity and induces the proliferative, migrating, and invading potentials of non-small cell lung cancer cells by binding to the miR-195." (PMID 33869744, 2021). "Coincidentally, the lncRNAs plasmacytoma variant translocation 1 (PVT1), diGeorge syndrome critical region gene 5 (DGCR5), and cytoskeleton regulator RNA (CYTOR) were confirmed to decrease the radiosensitivity of non-small cell lung cancer cells by sponging miR-195." (PMID 31391206, 2019).
liver cancer (8 papers, 2015 to 2024). An epithelial or non-epithelial malignant neoplasm that arises from the liver. "Previous studies have shown that CYTOR can promote liver cancer progression through regulation of the miRNA-125a-5p/LASP1 axis and miR-125b/SEMA4C axis." (PMID 36452343, 2022). "In CRC, CYTOR functions as a sponge to suppress the expression and function of miRNA, and CYTOR inhibition upregulates miR-215, which targets CKD13 to suppress the development of liver cancer." (PMID 36814556, 2023).